RN7SL173P (RNA, 7SL, cytoplasmic 173, pseudogene)
Gene: Miscellaneous RNA gene on chromosome 6 (158,437,797 to 158,438,088, forward strand). Ensembl gene ENSG00000243373.
Homologues: Orthologues: chimpanzee Metazoa_SRP (99% identical), macaque Metazoa_SRP (95% identical). Paralogues in human: RN7SL2 (80% identical), RN7SL1 (80% identical), RN7SL3 (79% identical), RN7SL625P (79% identical), RN7SL408P (79% identical), RN7SL326P (78% identical), RN7SL126P (78% identical), RN7SL230P (78% identical), RN7SL321P (78% identical), RN7SL786P (78% identical), RN7SL43P (77% identical), RN7SL448P (77% identical), and 698 more.